HIVEP2 (HIVEP zinc finger 2)
Description:
This protein specifically binds to the DNA sequence 5'-GGGACTTTCC-3' which is found in the enhancer elements of numerous viral promoters such as those of SV40, CMV, or HIV1. In addition, related sequences are found in the enhancer elements of a number of cellular promoters, including those of the class I MHC, interleukin-2 receptor, somatostatin receptor II, and interferon-beta genes. It may act in T-cell activation.
Synonyms: HIV-EP2; MBP-2; MIBP1; ZAS2; Schnurri-2; ZNF40B; MRD43; SHN2
Tractability: PROTAC: ubiquitination databases record sites on it; its protein half-life has been measured.
Target class: Transcription factor
Gene: Protein-coding gene on chromosome 6 (142,751,467 to 142,956,698, reverse strand). Ensembl gene ENSG00000010818.
Subcellular location: Nucleus
Subcellular location (Human Protein Atlas): Nucleoplasm
Gene Ontology:
Molecular function: protein binding; DNA binding; DNA-binding transcription factor activity, RNA polymerase II-specific; RNA polymerase II cis-regulatory region sequence-specific DNA binding
Biological process: regulation of transcription by RNA polymerase II
Cellular component: nucleoplasm; nucleus
Genetic constraint (gnomAD): Loss-of-function variants: 13 observed, 180.87 expected, observed/expected ratio (o/e) 0.0719, 90% interval 0.046 to 0.11. The upper end of that interval is the gene's LOEUF score, 0.11, which puts it in group 1 of 6, group 1 being the genes least tolerant of losing a copy. Missense variants: 2,509 observed, 3,091.8 expected, observed/expected ratio (o/e) 0.81, 90% interval 0.78 to 0.84. Synonymous variants: 1,158 observed, 1,171.9 expected, observed/expected ratio (o/e) 0.99, 90% interval 0.94 to 1.04.
Homologues: Orthologues: chimpanzee HIVEP2 (99% identical), macaque HIVEP2 (98% identical), pig HIVEP2 (92% identical), dog HIVEP2 (92% identical), rabbit HIVEP2 (92% identical), guinea pig HIVEP2 (88% identical), rat Hivep2 (88% identical), mouse Hivep2 (87% identical), tropical clawed frog hivep2 (59% identical), zebrafish hivep2a (45% identical). Paralogues in human: HIVEP3 (31% identical), HIVEP1 (28% identical), ZNF831 (12% identical), RREB1 (10% identical), SALL3 (7% identical), SALL1 (7% identical), SALL4 (6% identical), ZNF536 (6% identical), BCL11B (6% identical), BCL11A (5% identical), ZNF516 (5% identical), SALL2 (4% identical), and 2 more.
Diseases named in the same sentence as HIVEP2 in open-access papers:
HIVEP2 is named in the same sentence as 38 diseases in open-access papers, as found by Europe PMC text mining. Sharing a sentence is not in itself a finding about the gene and the disease. The quoted sentences say what the papers report.
schizophrenia (15 papers, 2013 to 2026). A major psychotic disorder characterized by abnormalities in the perception or expression of reality. "HIVEP2 has also been linked to schizophrenia and substance use disorders, and knockout mice for this gene show hyperactivity, anxiety, and schizophrenia-related behaviors, which is in line with the associations we found between ADHD and anxiety." (PMID 35052433, 2021). "We compared the mRNA levels of factors upstream of NF-κB expression in the cortex of Shn2 KO mice to determine which of the changes seen in high neuroinflammation schizophrenia could be caused by HIVEP2 deficiency." (PMID 32680547, 2020). "We speculate that this comparatively milder NF-κB induction may reflect schizophrenia-specific suppression possibly related to HIVEP2 deficiency in the cortex." (PMID 32680547, 2020). "NF-kappaB was observed to be over activated while its inhibitor, human immunodeficiency virus enhancer binding protein 2 (HIVEP2), was inactivated in the postmortem brain of patients with schizophrenia." (PMID 37520228, 2023). "In our previous study, we showed that the rescue of the iDG phenotype was accompanied by the rescue of nesting behavior deficits in Hivep2 KO mice, a mouse model of schizophrenia and ID." (PMID 36414974, 2022). "HIVEP2 mRNA reduction was specific to patients with schizophrenia who also had high neuroinflammatory status, and we also found decreases in NF-κB transcripts typically induced by activated microglia in mice lacking HIVEP2." (PMID 32680547, 2020). "In contrast, another NF-κB inhibitor, human immunodeficiency virus type 1 enhancer binding protein 2 (HIVEP2) is decreased in schizophrenia cortex compared to controls." (PMID 32680547, 2020). "Shn2 knockout mice exhibit behavioral abnormalities resembling symptoms of schizophrenia and HIVEP2-related intellectual disability as well as marked functional alterations in the soma and output synapse of the dentate granule cells (GCs)." (PMID 30285890, 2018). "In this study, we examined developmental changes in spine distribution in multiple mouse models of schizophrenia (Grin1 cKO, Hivep2 KO, and Setd1a cKO) and found that experience-dependent spine formation during adolescence, rather than pruning, was commonly affected." (PMID 41533795, 2026). "HIVEP2 deletion in mice leads to several schizophrenia-like behavioral and neuropathological phenotypes and allows us to test which NF-κB-related transcripts may be downstream of blunted HIVEP2 expression in schizophrenia or in controls." (PMID 32680547, 2020). "First, we studied Hivep2 (also known as Schnurri-2, coding for a transcription factor) KO mice because Hivep2 KO mice have been found to exhibit prominent behavioral abnormalities related to schizophrenia in the large-scale behavioral batteries (e.g., reduced prepulse inhibition and working memory)." (PMID 41533795, 2026). "However, the extent to which these changes are disease-specific, restricted to those with schizophrenia and high-neuroinflammatory status, or caused by loss of a key NF-κB inhibitor (HIVEP2) found in schizophrenia brain, has not been tested." (PMID 32680547, 2020). "HIVEP2 is decreased in the brain in high inflammation schizophrenia, and HIVEP2 (Shn2) deletion induces neuroinflammation in adult mice." (PMID 32680547, 2020). "HIVEP2, a protein that regulates NF-κB activity in the brain by preventing its target DNA-binding, is downregulated in the dorsolateral PFC of people with schizophrenia and cortical inflammation." (PMID 32680547, 2020). "Post-mortem prefrontal cortex samples were assessed in 141 human brains (69 controls and 72 schizophrenia) and 13 brains of wild-type mice and mice lacking HIVEP2 (6 wild-type, 7 knockout mice)." (PMID 32680547, 2020). "Among them, mice lacking Schnurri-2 (Shn2 or HIVEP2) have been proposed as a model of schizophrenia and intellectual disability." (PMID 30285890, 2018).
Intellectual disability (13 papers, 2017 to 2026). "Later studies in human showed that HIVEP2 haploinsufficiency is linked to various neuropsychiatric impairment including intellectual disability." (PMID 41533795, 2026). "The second, Hivep2, is a protein related to intellectual disability and specifically implicated in short-term synaptic plasticity." (PMID 40414897, 2025). "Hivep2, which encodes human immunodeficiency virus type I enhancer-binding protein 2, is associated with developmental delay, intellectual disability, and dysmorphic features." (PMID 35036173, 2021). "Mutations in a closely functionally related gene, HIVEP2, were recently shown to be associated with intellectual disability and developmental delay." (PMID 31620175, 2019). "Among them, HIVEP2 has been reported in patients characterized by developmental delay and intellectual disability, and CHD2 was found implicated in the development of selected neural circuits (i.e., cortical and hippocampal circuits) and long-term memory." (PMID 31652596, 2019). "More recently, whole exome sequencing studies demonstrated that nine individuals with intellectual disability have distinct de novo variants in HIVEP2, and they are diagnosed with “HIVEP2 syndrome”." (PMID 29233179, 2017). "For example, the low pH/high lactate group included SZ model Nrgn KO mice, SZ/intellectual disability (ID) models Ppp3r1 KO mice and Hivep2 (also known as Shn2) KO mice, AD model APP-J20 Tg mice, ASD model Chd8 KO mice, and social defeat stress-induced depression model mice." (PMID 38529532, 2024). "To date, HIVEP2 variants had been published in 14 cases with the last follow-up of age 5 to 24 years, and the clinical feature was nonspecific, including hypotonia, development delay, intellectual disability, and dysmorphic features." (PMID 33897753, 2021). "In humans, HIVEP2 encodes human immunodeficiency virus type I enhancer‐binding protein 2, which is a C2H2 zinc finger protein also known as the transcription factor ZAS2/MIBP1 and related to neurological disorders characterized by intellectual disability and physical characteristics." (PMID 33002329, 2020). "Previously, we proposed mice lacking Schnurri-2 (Shn2; also called major histocompatibility complex [MHC]-binding protein 2 [MBP-2], or human immunodeficiency virus type I enhancer binding protein 2 [HIVEP2]) as a schizophrenia and intellectual disability model with mild chronic inflammation." (PMID 29233179, 2017).
glioma (8 papers, 2020 to 2023). A benign or malignant brain and spinal cord tumor that arises from glial cells (astrocytes, oligodendrocytes, ependymal cells). "For instance, YTHDF2 facilitated m6A-dependent mRNA decay of LXRA and HIVEP2, which impacted the glioma patient survival." (PMID 37840133, 2023). "YTHDF2 facilitates m6A-dependent mRNA decay of LXRA and HIVEP2, which impacts the glioma patient survival." (PMID 33420027, 2021). "HIVEP2, also known as MIBP2 (c-myc intron binding protein 1), was not only described to control the expression of multiple genes, many of which are involved in brain development, but also to inhibit glioma growth." (PMID 32151286, 2020). "Moreover, YTHDF2 facilitates m6A-dependent mRNA decay of L-xylulose reductase (LXRA) and HIVEP zinc finger 2 (HIVEP2), which impacts the glioma patient survival." (PMID 35625706, 2022). "Overall, the overexpression of YTHDF2 may simultaneously accelerate the degradation of UBXN1, LXRα, and HIVEP2 mRNAs, promoting glioma development through a complex network of actions." (PMID 35682599, 2022). "HIVEP2 level is known to decreases in higher grade of glioma and most significantly in GBM." (PMID 33420027, 2021). "Importantly, in the TCGA glioma dataset, we found that a low LXRA and HIVEP2 co-expression predicts worse prognosis of glioma patients compared with a high co-expression." (PMID 33420027, 2021). "In glioma, YTHDF2 is essential for tumor cell proliferation by facilitating LXRA and HIVEP2 decay." (PMID 37438359, 2023). "In gliomas, elevated YTHDF2 expression could suppress the expression of LXRα and HIVEP2 via m6A-dependent mRNA clearance, which is required for GSC growth, invasion, and tumor formation in vivo." (PMID 34246306, 2021).
Anxiety (5 papers, 2014 to 2023). Intense feelings of nervousness, tension, or panic often arise in response to interpersonal stresses. "In the case of anxiety, we found a nominal association with the HIVEP2 gene using a GWAS of 7016 cases and 14,745 controls." (PMID 35052433, 2021). "The region at ~34 Mb on CFA1, associated with Separation anxiety, includes HIVEP2 and AIG2, which have been previously identified as positional candidate genes in a GWAS on affiliative social behavior in humans." (PMID 31611599, 2019). "In addition, working memory issues, elevated anxiety, and hyperactivity are all present in HIVEP2-knockout mice." (PMID 36979479, 2023). "Based on DisgeNet data, Acsl4, Clock, Scn2a, and Hivep2 are confirmed as anxiety-related genes." (PMID 36979479, 2023).
autism (2 papers, 2021 to 2025). Persistent deficits in social interaction and communication and interaction as well as a markedly restricted repertoire of activity and interest as well as repetitive patterns of behavior. "Notably, HIVEP2 is a highly confident autism risk gene according to the Simons Foundation Autism Research Initiative database." (PMID 40446031, 2025). "HIVEP2 and FOXP1 code for transcription factors and both have previously been related to autism." (PMID 35052433, 2021).
neuroblastoma (2 papers, 2019 to 2022). Neuroblastoma (NB) is the most common solid, extracranial childhood tumor. "WGS detected only two somatic nonsynonymous alterations affecting CEP170 and HIVEP2, both genes without established connection to neuroblastoma or cancer in general." (PMID 36140661, 2022).
asthma (1 paper, 2020). "We report that THSD4, HIVEP2, DPP10, HDAC9 and other genes within inflammatory response pathways and with definitive roles in asthma susceptibility, severity, and exacerbations, are also asthma pharmacogenes." (PMID 32119686, 2020). "First, the age-by-genotype interaction analysis identified two SNPs, rs34631960 in THSD4 and rs2328386 in HIVEP2, that met genome-wide significance based on meta-analysis in 1,321 pediatric and adult patients with asthma who were taking ICS." (PMID 32119686, 2020). "HIVEP2, also known as Schnurri (Shn)-2, contributes to asthma pathogenesis through its role as an NFkB binding protein, and regulates Th2 cell differentiation and responses." (PMID 32119686, 2020). "In addition to THSD4 and HIVEP2, age-by-genotype interactions also prioritized genes previously identified as asthma candidate genes, including DPP10, HDAC9, TBXAS1, FBXL7, and GSDMB/ORMDL3, as pharmacogenomic loci as well." (PMID 32119686, 2020). "Despite this, the present study, in addition to previous literature defining roles for both THSD4 and HIVEP2 in asthma, show that these may represent candidate genes for which additional molecular studies are warranted in order to clarify their roles in asthma and differential ICS response." (PMID 32119686, 2020).
atherosclerosis (1 paper, 2022). A disease characterized by the build-up of fatty material and calcium deposition in the arterial wall resulting in partial or complete occlusion of the arterial lumen. "Further genes upregulated in cardiac art ECs in obesity, including Hivep2 and Cfdp1, were associated with atherosclerosis, while CDKN1A, the gene encoding the senescence factor p21, was associated with heart failure." (PMID 36400935, 2022).
bipolar disorder (1 paper, 2021). A disorder of the brain that causes unusual shifts in mood, energy, activity levels and the ability to carry out day-to-day tasks. "Finally, in contrast, mRNA levels for HIVEP2, an NF-κB site-binding protein that inhibits NF-κB transcriptional activity, were lower in bipolar disorder subjects and were inversely correlated with mRNA levels for the other NF-κB-related markers." (PMID 33436571, 2021). "In addition, HIVEP2 mRNA levels were lower in 71% of bipolar disorder subjects relative to their matched comparison subject." (PMID 33436571, 2021).
brain tumors (1 paper, 2021). "Depletion of LXRα and HIVEP2 largely abolished tumor growth inhibition by YTHDF2 knockdown and drove the brain tumors more invasive as compared to those of YTHDF2 knockdown." (PMID 33420027, 2021).
colorectal cancer (1 paper, 2017). A primary or metastatic malignant neoplasm that affects the colon or rectum. "Indeed, our translatome profiling and validation process showed that the distribution of HIVEP2 mRNA was significantly increased in polysomes compared to non-polysomes in response to 5-FU in a panel of three colorectal cancer cell lines." (PMID 28515355, 2017).
systemic lupus erythematosus (1 paper, 2021). An autoimmune multi-organ disease typically associated with vasculopathy and autoantibody production. "For example, overexpression of lncRNA DQ786243 was found in patients with Crohn’s disease, overexpression of lncRNA HIVEP2 in patients with systemic lupus erythematosus (SLE), lncRNA SAS-ZFAT plays a role in autoimmune thyroid disease." (PMID 33572313, 2021).
tumor (6 papers, 2021 to 2024). "Moreover, depletion of YTHDF2 prolonged the survival of tumor-bearing mice as compared with the control, whereas LXRα and HIVEP2 knockdown reversed the effect of YTHDF2 depletion on the survival of tumor-bearing mice." (PMID 33420027, 2021). "Furthermore, we confirmed that the control tumor xenografts have very low expression of LXRα and HIVEP2 proteins but depletion of YTHDF2 increased the expression of LXRα and HIVEP2." (PMID 33420027, 2021). "The expression of CTGF and MYB was significantly higher in HCC tissues than that in the adjacent non-tumor tissues (p < 0.05), while the expression of BCLAF1, IFNGR1, and HIVEP2 was significantly lower in HCC tissues than in adjacent non-tumor tissues (p < 0.05)." (PMID 34616668, 2021).
cancer (5 papers, 2011 to 2022). A tumor composed of atypical neoplastic, often pleomorphic cells that invade other tissues. "The transcriptional levels of HIVEP2/3 were remarkably elevated in AML patients compared to healthy donors and displayed the broadest range of median expression levels among pan‐cancer types." (PMID 35535739, 2022). "HIVEP2 is a transcription factor whose downstream target, SSTR2, inhibits cancer cell proliferation." (PMID 34246306, 2021).
neurodevelopmental disorder (2 papers, 2025). A behavioral and cognitive disorder with onset during the developmental period that involves impaired or aberrant development of intellectual, motor, or social functions. "For instance, dysregulation of Hivep2 and Bcl11a has been implicated in neurodevelopmental disorders and synaptic dysfunction, and our findings suggest their roles extend to mediating neuronal vulnerability in H-I injury." (PMID 40618091, 2025).
neurological disorders (1 paper, 2020). "Moreover, HIVEP2 is related to neurological disorders in humans and is associated with numerous regulatory pathways involved in cellular immunity and development processes." (PMID 33002329, 2020).
HIVEP2 also shares sentences with these, for which no sentence is quoted: developmental delay (3 papers); autism spectrum disorder (2); 3-methylglutaconic aciduria type 1 (1); Alzheimer disease (1); anxiety disorder (1); bipolar I disorder (1); bipolar II disorder (1); cognitive deficits (1); depression (1); Encephalopathy (1); epilepsy (1); Epileptic encephalopathy (1); genetic disorders (1); glioblastoma (1); heart failure (1); hereditary neuralgic amyotrophy (1); infection (1); ischemia (1); microcephaly (1); Obesity (1); psychiatric disorder (1); Rett syndrome (1).